CDK15 (cyclin dependent kinase 15)
Description:
Serine/threonine-protein kinase that acts like an antiapoptotic protein that counters TRAIL/TNFSF10-induced apoptosis by inducing phosphorylation of BIRC5 at 'Thr-34'.
Synonyms: ALS2CR7; PFTK2; PFTAIRE2
Tractability: Small molecule: a drug acting on it is in phase 2 or 3 trials; a high-quality ligand is known; it belongs to a druggable protein family. PROTAC: ubiquitination databases record sites on it; a small molecule that binds it is known.
Target class: Enzyme; CMGC protein kinase CDK family; CMGC protein kinase PFTAIRE; CMGC protein kinase group; Kinase; Protein Kinase
Chemical probes: JA397 (high quality)
Gene: Protein-coding gene on chromosome 2 (201,790,461 to 201,895,550, forward strand). Ensembl gene ENSG00000138395.
Subcellular location (Human Protein Atlas): Golgi apparatus; Nucleoplasm
Gene Ontology:
Molecular function: protein binding; protein serine kinase activity; protein serine/threonine kinase activity; cyclin binding; cyclin-dependent protein serine/threonine kinase activity; ATP binding; protein kinase activity
Biological process: regulation of cell cycle phase transition
Cellular component: cyclin-dependent protein kinase holoenzyme complex; cytoplasm; cytosol
Genetic constraint (gnomAD): Loss-of-function variants: 53 observed, 51.59 expected, observed/expected ratio (o/e) 1.03, 90% interval 0.82 to 1.29. The upper end of that interval is the gene's LOEUF score, 1.29, which puts it in group 5 of 6, group 1 being the genes least tolerant of losing a copy. Missense variants: 457 observed, 466.97 expected, observed/expected ratio (o/e) 0.98, 90% interval 0.91 to 1.06. Synonymous variants: 169 observed, 174.74 expected, observed/expected ratio (o/e) 0.97, 90% interval 0.85 to 1.1.
Homologues: Orthologues: macaque CDK15 (96% identical), dog CDK15 (93% identical), pig CDK15 (91% identical), rat Cdk15 (91% identical), chimpanzee CDK15 (91% identical), rabbit CDK15 (90% identical), mouse Cdk15 (90% identical), guinea pig CDK15 (87% identical), tropical clawed frog cdk15 (68% identical), zebrafish cdk15 (58% identical). Paralogues in human: CDK14 (56% identical), CDK16 (44% identical), CDK17 (43% identical), CDK18 (43% identical), CDK5 (35% identical), CDK11B (34% identical), CDK11A (34% identical), CDK3 (34% identical), CDK2 (31% identical), CDK1 (31% identical), CDK12 (31% identical), CDK13 (31% identical), and 14 more.
Diseases named in the same sentence as CDK15 in open-access papers:
CDK15 is named in the same sentence as 15 diseases in open-access papers, as found by Europe PMC text mining. Sharing a sentence is not in itself a finding about the gene and the disease. The quoted sentences say what the papers report.
breast carcinoma (3 papers, 2019 to 2025). "PCR result found that CDK15 mRNA level remains relatively constant among all of cell lines, suggesting that the loss of CDK15 in breast cancer might be due to post-transcriptional regulation, which is consistent to the data that PA28α/β are responsible for down-regulation of protein level of CDK15." (PMID 31824858, 2019). "As expected, CDK15 expression was also significantly up-regulated in breast cancer cells when β5i had been knocked down." (PMID 31824858, 2019). "Here, our analyses in breast tumor specimens and breast cancer cell lines indicated that CDK15 protein level is down-regulated in breast cancer, while its mRNA expression keeps constant." (PMID 31824858, 2019). "To study the relevance of CDK15 to breast cancer, we detected CDK15 protein expression in breast cancer specimens and corresponding normal tissues." (PMID 31824858, 2019). "Immunoblot data revealed the expression of CDK15 is frequently decreased in a range of specimens including luminal breast cancer and basal-like subtype." (PMID 31824858, 2019). "Furthermore, PA28αβ was suggested to promote breast cancer cell invasion and metastasis by promoting proteasomal degradation of cyclin-dependent kinase 15 (CDK15)." (PMID 40563520, 2025). "Our study also reveals CDK15 as a suppressor of breast cancer cell invasion and metastasis." (PMID 31824858, 2019). "Meanwhile, we evaluated the expression intensity of CDK15 using immunohistochemical staining in 53 pairs of breast cancer specimen and adjacent non-tumor tissue." (PMID 31824858, 2019). "We further measured the mRNA expression status of CDK15 in a group of breast cell lines, including human normal mammary epithelial cells MCF10A and MCF12A, basal-like breast cancer cells MDA-MB-231 and BT549, luminal breast cancer cells BT474, MDA-MB-453, and T47D." (PMID 31824858, 2019).
breast tumor (3 papers, 2019 to 2025). "Our data further indicate that the loss of CDK15 is important for breast tumor cell invasion and metastasis." (PMID 31824858, 2019). "IF staining in matched pairs of HR-deleted breast tumors and matched normal tissue revealed an increase in H3K9 methylation in the tumor, coupled with increased expression of CDK15 and CA9 but decreased expression of CELF2, consistent with the qRT-PCR and RNA-seq results." (PMID 36230572, 2022).
lung adenocarcinoma (2 papers, 2020 to 2026). A carcinoma that arises from the lung and is characterized by the presence of malignant glandular epithelial cells. "In summary, we represented a rare double ALK fusion composed of a classic fusion variant of EML4-ALK and a newly discovered CDK15-ALK in a lung adenocarcinoma." (PMID 33157918, 2020). "Here we report a rare double ALK fusion variant, EML4-ALK and CDK15-ALK in a patient with lung adenocarcinoma who responded well to crizotinib." (PMID 33157918, 2020). "Together, we identified a rare double ALK fusion variant, EML4-ALK and CDK15-ALK, in a patient with lung adenocarcinoma." (PMID 33157918, 2020). "In this report, we identified a rare double ALK fusion, EML4-ALK and CDK15-ALK, in the patient with lung adenocarcinoma." (PMID 33157918, 2020).
nasopharyngeal carcinoma (2 papers, 2019 to 2025). A carcinoma arising from the nasopharyngeal epithelium. "Epstein-Barr virus (EBV) integration can decrease the expression of CDK15 gene in nasopharyngeal carcinomas (NPCs), implicating that downregulation of CDK15 may contribute to tumor development." (PMID 39800748, 2025).
cervical cancer (1 paper, 2026). A primary or metastatic malignant neoplasm involving the cervix. "Differences in CDK15 and L1CAM L1 expression in cervical cancer tissues were compared across subgroups stratified by different clinicopathological characteristics, including age and International Federation of Gynecology and Obstetrics(FIGO) stage." (PMID 41994380, 2026). "Consequently, CDK15 and L1CAM hold promise as novel prognostic biomarkers and potential therapeutic targets for cervical cancer." (PMID 41994380, 2026).
gastric cancer (1 paper, 2026). A primary or metastatic malignant neoplasm involving the stomach. "The two loci (DOCK10 and FCN1-FCN2) replicated from CoGaPro1, and the 11 loci replicated from CoGaPro2 (CDK15, CROCC2-SNED1, TLR2-RNF175-SFRP2, WWC2, RELN, ZMYM5-ZMYM2, KLF12, SKAP1, CABLES2, and MIR630) gave further support for these genes being associated with a risk of CRC and gastric cancer." (PMID 41516419, 2026).
lymphoma (1 paper, 2021). A malignant (clonal) proliferation of B- lymphocytes or T- lymphocytes which involves the lymph nodes, bone marrow and/or extranodal sites. "Moreover, 47 cell proliferation-associated genes were found downregulated in Ri-1 cells under hypoxia, including cyclin CCNB1, and cyclin-dependent kinases CDK14, CDK15, and CDK16, which have significant involvement in the lymphoma pathogenesis." (PMID 34440794, 2021).
tumor (7 papers, 2019 to 2026). "This combinatorial approach elicited T cells against specific neoantigens (LNPEP, NDUFS6, MYO15, and CDK15) that were positively correlated with reduced tumor burden in the treated animals." (PMID 33723260, 2021). "In BC cells, PA28α/β downregulates the expression of serine/threonine-protein kinase (CDK15) which leads to enhanced proliferation, migration, and invasion of tumor cells." (PMID 34885122, 2021). "The study implicates the working mechanism of PA28α/β mediated tumor cell invasion and metastasis, also the post-translational regulation of CDK15 protein." (PMID 31824858, 2019). "In addition, analyses of wound healing in various groups indicated that the CDK15-overexpressing tumor cells had significantly weaker migratory ability than vector control cells." (PMID 31824858, 2019). "Our follow-up study will focus on whether immunoproteasome is responsible for direct degradation of CDK15 and search of other downstream target proteins of immunoproteasome in tumor cells." (PMID 31824858, 2019). "Few notions are available on the possible role of CDK14 and CDK15 in cancer progression showing some degree of variability among the different tumors and or the different studies resulting in a still unclear picture of their possible involvement in tumor progression." (PMID 39800748, 2025). "CDK15 reduction inhibited cell proliferation, anchorage-independent growth of CRC cells and tumor progression in patient-derived xenograft (PDX) model, through the regulation of β-catenin and MEK/ERK signaling cascades to drive oncogenic pathway of CRC cells, both in vivo and in vitro." (PMID 39800748, 2025). "CCK8 and cell cycle analyses confirmed that alteration of intrinsic CDK15 level does not influence the tumor cell proliferation potential." (PMID 31824858, 2019). "In almost all cases, CDK15 expression in paired non-tumor tissues was positive or strongly positive, while most of tumor specimens showed negative or weak CDK15 expression." (PMID 31824858, 2019). "In addition, the cell cycle distribution did not alter significantly in CDK15-overexpressing tumor cells compared with their vector control cells." (PMID 31824858, 2019). "Meanwhile, downregulation of CDK15 may be not the unique working mechanism of 11S in the facilitation of tumor cell motility, we cannot exclude the possibility that other downstream proteins are involved in the pro-invasive and pro-metastatic function of PA28α/β." (PMID 31824858, 2019).
cancer (5 papers, 2019 to 2025). A tumor composed of atypical neoplastic, often pleomorphic cells that invade other tissues. "CDK15 Also CDK15 has been associated with cancer progression, although its effects appear to be context dependent." (PMID 39800748, 2025). "The authors identified cyclin-dependent kinase 15 (CDK15) as negative regulator of cancer cell motility and as a possible target of the 11S regulator and immunoproteasome." (PMID 37261527, 2023). "Many synthetic lethalities involved CDK proteins that had yet to be investigated as anti-cancer drug targets, such as the transcriptional regulators CDK11B and CDK15." (PMID 37169829, 2023). "PFTAIRE2/PFTK2/Als2cr7/ CDK15 is recognized in GenBank database and has been reported for its role in conferring resistance to tumor necrosis factor-related apoptosis-inducing ligand (TRAIL) in cancer cells." (PMID 37907898, 2023).
CDK15 also shares sentences with these, for which no sentence is quoted: amyotrophic lateral sclerosis 2 (1 paper); colon cancer (1); insomnia (1); lung carcinoma (1); lymph node metastasis (1); migraine (1).